ADAM10 (ADAM metallopeptidase domain 10)
Diseases named in the same sentence as ADAM10 in open-access papers (continued):
Sharing a sentence is not in itself a finding about the gene and the disease.
infection (continued). "Connecting these dots, we were able to show that while in LD-S-infected-macrophages, Furin was mostly restricted to a perinuclear localization, in response to LD-R-infection, they were mostly present on the MФ surface co-localizing with ADAM10 to activate it (Fig 6andS3 Video)." (PMID 39888953, 2025). "Like S. aureus, many pathogens utilize PFTs or other membrane-injurious cytotoxins to damage and manipulate the endothelium, raising the possibility that these virulence factors may couple intravascular infection with the observed dependence on ADAM10." (PMID 37788087, 2023). "As EGFR family member activation is implicated in infection with viruses from various families including DNA and RNA viruses and ADAM17 was reported as a papilloma virus entry factor, we asked how specific the observed ADAM10 effect was." (PMID 37967063, 2023). "Moreover, the addition of GI254023X at different time points during infection allowed us to clarify if additional steps in the HCV life cycle are affected by ADAM10 depletion." (PMID 37967063, 2023). "We next assessed whether platelet aggregation within the hepatic vasculature was altered in an ADAM10-dependent manner following infection with these pathogens." (PMID 37788087, 2023). "Thus, the ADAM10 inhibitor inhibits S. grimesii invasion only when Ca2+ accumulates in host cells upon their infection with bacteria." (PMID 38069398, 2023). "Apparently, as a result of infection with S. grimesii, Ca2+ accumulates in the host cells and may activate ADAM10 sheddase, which can promote invasion by cleaving E-cadherin and, as a result, triggering EGFR signaling." (PMID 38069398, 2023). "Therefore, we used an ADAM10 inhibitor (GI254023X, a competive inhibitor with 100-fold higher specificity for ADAM10 versus ADAM17) during infection to increase peripheral resistance and vessel stiffness simultaneously." (PMID 35446924, 2022). "We next examined whether ADAM10 activity may influence transepithelial migration of THP-1 cells during infection with P. aeruginosa." (PMID 35163191, 2022). "Interestingly, the mature form of ADAM10 was vanished in the cell lysate after 2 h of infection, while the pro-from stayed constant." (PMID 35163191, 2022). "Interestingly, infection of A549 cells with P. aeruginosa for 2 h resulted in ADAM10 activation although the presence of mature ADAM10 was reduced on the cell surface as well as in the cell lysates." (PMID 35163191, 2022). "Here, we investigated the regulation of ADAM10 in A549 cells (alveolar adenocarcinoma cells) and human small airway epithelial cells (HSAEpC) during infection and sterile inflammation using Western blot (cell lysates) and analysis of surface expression on intact cells." (PMID 35163191, 2022). "Both S and ACE2 are also required for lung cell infection, raising the possibility that syncytia formation may also depend on ADAM10 and/or ADAM17 and may be blocked by metalloprotease inhibitors." (PMID 35527514, 2022). "We could show that ADAM10 is upregulated and activated upon infection with P. aeruginosa and one of its major virulence factors ExoA, but apparently not upon encounter with S. pneumoniae." (PMID 35163191, 2022). "Furthermore, IL-1beta and TNF alpha have been shown to induce the acute release of ACE2, which supports the protective role of ACE2 against spike-driven infection and ADAM10 regulation of ACE2 cleavage." (PMID 34356057, 2021). "Tissue damage, resolution of inflammation, and systemic changes: There exist several evidences that ADAM10 does not only act in the initial phase of infection but is also involved in the development of tissue damage, the resolution of inflammation or development of systemic effects." (PMID 33392273, 2020). "The enhancement of ADAM10 proteolytic activity by Hla is clearly tied to that aspect of infection pathogenesis, which is likely important for the bacteria to establish invasive infection of the tissues the toxin is acting on." (PMID 27043625, 2016).
infection (continued). "Hla targets ADAM-10 resulting in E-cadherin disruption and invasive infection in the lung." (PMID 25880560, 2015). "To determine whether over-expression of ADAM10 increases HIV-1 replication and infection, we obtained a human ADAM10 plasmid from Dr. Stefan Lichtenthaler (LMU Munich, Germany)." (PMID 21569301, 2011). "Thus, the pathogen-specific activation of ADAM10 through infection with P. aeruginosa is rather dependent on the pathogen’s toxin repertoire than the particle itself and might be triggered by intracellular calcium increase through calcium influx." (PMID 35163191, 2022). "Thus, ADAM10 may fulfill several pro-inflammatory functions during infection by orchestrating protein permeability, transepithelial migration as well as epithelial damage and regeneration/migration." (PMID 35163191, 2022). "Furthermore, the cells were incubated with an ADAM10 inhibitor after infection with LV3-miR-23b to validate whether miR-23b negatively regulated LPS-induced inflammatory responses by targeting ADAM10 in human THP-1 monocytes." (PMID 31780861, 2019). "Additionally, mice deficient for expression of the AT receptor, ADAM10, at the site of infection were resistant to infection with WT S. aureus and did not exhibit dermonecrosis." (PMID 24098366, 2013). "Interestingly, we found that while the metalloprotease domain of ADAM10 is not required for HIV-1 replication, ADAM15 and γ-secretase (which proteolytically release the extracellular and intracellular domains of ADAM10 from the plasma membrane, respectively) do support productive infection." (PMID 21569301, 2011). "We also observed that ADAM10 and ADAM17 levels were elevated shortly after infection but decreased below control levels by the final time point (day 120)." (PMID 40725601, 2025). "An interesting possibility is that ADAM10 and ADAM17 direct trafficking of CXCR6+ T cells to different tissues as a consequence of their increased activity upon infection of parenchymal cells by particular pathogens." (PMID 40043065, 2025). "Both compounds inhibited the X4 tropic HIV-1LAI infections similar to their inhibitions to the R5 tropic HIV-1BAL, suggesting ADAM10 and 17 are also involved in X4 tropic HIV-1 infections." (PMID 38572241, 2024). "Future studies on these zoonotic RNA viruses will clarify a potential role of ADAM10 and ADAM17 in infection." (PMID 37967063, 2023). "For both ADAM10 knock‐out cell lines, BB94 treatment further reduced infection to the level of the treated NTC control cells." (PMID 35527514, 2022). "In contrast to ADAM10, both single knock‐outs of ADAM17 reduced infection by 40–50%, and this rate was further reduced by the addition of BB94." (PMID 35527514, 2022). "Here, we demonstrate, for the first time, that early in infection, mitochondrial targeting of Map, particularly via its MTR motif, plays a role in activating the sheddase activity of ADAM10." (PMID 32934081, 2020). "ADAM10 and ADAM17 together with ADAM8 and ADAM9 seem to be the most relevant ADAM proteases in infection; however, some studies point toward an additional influence of ADAM12, ADAM15, and ADAM33." (PMID 33392273, 2020). "Infection of astrocytes with this intracellular pathogen showed an increase of BACE and PSEN1 expression, whereas the activity of ADAM10 was reduced, resulting in enhanced production of beta-amyloid." (PMID 33392273, 2020). "ADAM10 E384A and wild type (wt) ADAM10 plasmids were transfected into U373-MAGI-CCR5 cells 48 h prior to infection with HIV-SF162 (MOI = 0.1)." (PMID 21569301, 2011). "ADAM10 did not influence infection with other enveloped RNA viruses such as alphaviruses and a common cold coronavirus." (PMID 37967063, 2023). "S. aureus recovery from multiple tissues was comparable in control and VE-Cad ADAM10–/– mice 24 hours after infection, suggesting that the improved survival of VE-Cad ADAM10–/– mice was not simply related to early bacterial control." (PMID 37788087, 2023).
infection (continued). "In contrast, platelet thrombus formation was indistinguishable in control and VE-Cad ADAM10–/– mice after infection with GBS or C. albicans." (PMID 37788087, 2023). "In contrast, infection with the Gram-positive bacterium S. pneumoniae exerted no impact on ADAM10 protein expression/maturation and surface localization." (PMID 35163191, 2022). "In infection experiments, we demonstrated hDsg2 shedding from H. pylori-colonized MKN28 and NCI-N87 cells independently of pathogen-induced matrix-metalloproteases or ADAM10 and ADAM17." (PMID 34742300, 2021). "We hypothesize that the triggering of the ADAM10-MAPK/ERK signaling by Map in an early infection event, which is counteracted by EspH in a later infection time, may play a crucial role in the induction of EPEC pathogenesis." (PMID 32934081, 2020). "Cell infection with EPEC-map+MapΔMTS-EspH1–25 caused diminished pERK, pMEK (data not shown), pEGFR, and ADAM10 activity, reaching intermediate values between those attained upon infection with EPEC-map and EPEC-map+Mapwt." (PMID 32934081, 2020). "Cell infection with EPEC-map+MapΔ101–152 resulted in a significant reduction in pMEK (data not shown), pERK, pEGFR, and ADAM10 activity, reaching the minimal values exhibited upon infection with EPEC-map." (PMID 32934081, 2020). "The transcripts of APP, ADAM10, BACE1, and subunits of the γ-secretase complex (PSEN1, PSEN2 APH1A and NCSTN) were significantly upregulated (p < 0.05) in at least one of the 4 investigated timepoints post-infection." (PMID 30786875, 2019). "The infection of the ADAM10-negative-hCMEC/D3 cells by the WT meningococcal strain was associated with no change of membranous EPCR expression." (PMID 29630665, 2018). "Co-silencing of LEDGF with ADAM10 resulted in a slightly more robust reduction of infection than with Nup153, but both combinations were more efficient than silencing LEDGF alone, and co-silencing of ADAM10 and Nup153 also resulted in lower infectivity than silencing of each one individually." (PMID 23028330, 2012). "In agreement, Western blots revealed that production of the viral Env and p24 proteins were significantly inhibited between days 4-7 post-infection in primary macrophages following ADAM10 silencing (data not shown)." (PMID 21569301, 2011). "To inform an understanding of microvascular injury induced by S. aureus in situ, we used 2-photon microscopy to visualize platelet-endothelial interactions within the hepatic vasculature following infection of VE-Cad ADAM10–/– mice and matched controls with a nonlethal inoculum of S. aureus." (PMID 37788087, 2023). "Despite the lack of changes in ADAM10 expression patterns upon infection with S." (PMID 35163191, 2022). "We conclude that different proteases, including TMPRSS2, ADAM10, ADAM17, and potentially others, may prime S2 and, thus, facilitate: (i) infection through the fusion of the SARS‐CoV‐2 virus with host cells, or (ii) syncytia formation of S‐expressing SARS‐CoV‐2‐infected cells with host cells." (PMID 35527514, 2022). "ADAM10 KO1 showed a mild and variable reduction of infection, but this was not seen for ADAM10 KO2 cells, demonstrating that ADAM10‐deficiency alone does not have a major impact on A549‐ACE2 infection." (PMID 35527514, 2022). "Moreover, there was no release of soluble forms of EPCR in the supernatant of ADAM10-negative-hCMEC/D3 upon infection." (PMID 29630665, 2018). "Whether or not the apparent link between basal nutrient stress and expression of ADAM10 was shaped by co-evolution of S. aureus and humans, it may also bear on functions of ADAM10 that are not related to infection." (PMID 26284068, 2015). "Double knock‐out (ADAM10/17 KO) cells lacking both ADAM10 and ADAM17 showed the strongest reduction of infection similar to BB94‐treated NTC cells, and this double knock‐out effect was not significantly further reduced with additional BB94 treatment." (PMID 35527514, 2022).
infection (continued). "Importantly, DMDP, an MMP-1 inhibitor that did not inhibit ADAM10 and 17 enzymatic activities nor CD62L shedding, failed to inhibit HIV-1BAL infections." (PMID 38572241, 2024). "However, while there is known promotion of trans-infection of HIV-1 secondary to interaction with the adhesion molecules, C-type lectins DC-SIGN and DC-SIGNR, the data presented above do not support a role in cell entry for ADAM10." (PMID 21569301, 2011).
neurodegenerative disease (19 papers, 2016 to 2025). A disorder of the central nervous system characterized by gradual and progressive loss of neural tissue and neurologic function. "ADAM10 and CCDC6 were the shared causal genes for the psychiatric and neurodegenerative diseases at both the mRNA and protein levels." (PMID 35882878, 2022). "In many studies, it was proven to be effective in the treatment of neurodegenerative diseases since the increase of ADAM10 activity, which was the main α-secretase, which broke the APP, protected the brain from the accumulation of Aβ in AD." (PMID 35957121, 2022). "As increased ADAM10 activity protects the brain from β-amyloid deposition in AD, this strategy has been proved to be effective in treating neurodegenerative diseases, including AD." (PMID 29382156, 2018). "Thus, increasing ADAM10 activity has been proposed an attractive target for the treatment of neurodegenerative diseases and it appears to be timely to investigate the physiological mechanisms regulating ADAM10 expression." (PMID 28367112, 2017). "Therefore, we extended our assessment of CAP2, DLG1, and ADAM10 gene and protein expression levels to the post-mortem superior frontal gyrus (SFG) of patients affected by neurodegenerative diseases such as PD and AD." (PMID 35163460, 2022).
cardiovascular disease (6 papers, 2017 to 2025). "Our observations demonstrate that exposure to IR activates ADAM10 to cleave VE-cadherin leading to augmented endothelium permeability; a feature that can lead to the development of atherosclerotic plaques and increase the risk of cardiovascular disease." (PMID 29137243, 2017). "Recently, this mechanism of ADAM10-mediated breakdown of VE-cadherin upon exposure to ionizing radiation, leading to increased endothelial permeability, has been described by Kabacik and Raj in the context of increased risk of cardiovascular diseases after radiotherapy." (PMID 31619190, 2019). "Serum ADAM10 level was higher in subjects with cardiovascular disease (51.3 ng/mL [27.2‐74.1] vs 40.7 ng/mL [22.9‐64.7], respectively; P = .03)." (PMID 35705192, 2022). "LOX‐1 is one of the substrates of ADAM10 and plays a pro‐atherogenic role in the development and progression of cardiovascular disease." (PMID 35705192, 2022). "For instance, strong inflammation and cardiovascular disease lead to an upregulation of ADAM metalloproteases (A Disintegrin and Metalloproteinase, ADAM10/17), which cleave membrane-bound DLL1." (PMID 40775336, 2025).
neurological diseases (6 papers, 2015 to 2025). "Although extensive research has examined the role of ADAM10 in neurological disorders, very little attention has been focused on ADAM10 in ASD." (PMID 41614744, 2025). "For the neurological diseases, miR-144 elevated in the early stage of AD patients and induced the depletion of ADAM10, which forced metabolism of amyloid β-peptide (Aβ) to protect the brain." (PMID 33510702, 2020). "Taking together, our results indicate a positive role of PLD1 in synaptogenesis by inhibiting the ADAM10 mediated N-cadherin cleavage and provide new therapeutic clues for some neurological diseases." (PMID 28729535, 2017). "Finally we found that PLD1 promotes the dendritic spine development by preventing N-cadherin from being cleaved by ADAM10, suggesting a potential role of PLD1 as an important regulator and a novel therapeutic target in neurological diseases." (PMID 28729535, 2017).
psychiatric disorder (5 papers, 2018 to 2023). A disorder characterized by behavioral and/or psychological abnormalities, often accompanied by physical symptoms. "TRP channels, as well as ADAM10, are expressed in central nervous system neurons and are associated with psychiatric disorders." (PMID 36668668, 2023). "Despite the crucial role of Adam10 in AD, recent studies indicate that Adam10 may contribute to other neurological and psychiatric disease." (PMID 30075790, 2018).
renal diseases (5 papers, 2010 to 2023). "The activation of ADAM10 initiates an inflammatory and fibrotic response to renal diseases, including ARF, and recent studies have shown a link between ADAM10 and coagulation in kidney disease." (PMID 37513824, 2023). "ADAM10 is expressed in renal tubular cells and affects the expression of specific brush border genes, and its activation is involved in some renal diseases." (PMID 30460232, 2018). "By being released into urine, the shedding products could be useful for biomarkers of renal diseases, but ADAM10 and 17 per se are also notable as biomarkers." (PMID 30460232, 2018). "Furthermore, ADAM10 has effects some renal diseases such as lupus nephritis, arterionephrosclerosis, and DN." (PMID 30460232, 2018). "In addition, we detected ADAM10 in urinary podocytes from patients with kidney diseases and in tissue sections of normal human kidney." (PMID 20070888, 2010). "Although ADAM10 and ADAM17 are clearly involved in both CKD and CVD, yet are more elaborately studied in the context of CVD, the role of ADAMs in the progression of renal disease and especially their role in cardiorenal disease is thus far a rather understudied field of research." (PMID 37108478, 2023).
bacterial infection (4 papers, 2017 to 2025). "Initially, both vibrios elicited a proteomic response related to bacterial infection and immunity (e.g., ADAM10, RAPTOR), followed by an increase of lysosomal and endocytic proteins (e.g., NPC2) after 60 min." (PMID 40576359, 2025).
brain diseases (2 papers, 2019 to 2020). "ADAM10 is involved in neurodevelopment, synaptic plasticity, and dendritic spine morphology, and it has been well studied as a therapeutic target for brain diseases." (PMID 33246507, 2020).
gastrointestinal tumor (2 papers, 2020 to 2022). "The monoclonal antibody 8C7 was directed against an active conformation of ADAM10 and was shown to inhibit lymphoma growth in a xenograft model and gastrointestinal tumour growth in a genetic mouse model." (PMID 32698506, 2020).
cardiac disease (1 paper, 2021). "Furthermore, to identify whether ADAM10 was altered in cardiac disease, the expression of ADAM10 was examined." (PMID 34522779, 2021).
hematological malignancies (1 paper, 2025). "Moreover, the significant difference in ADAM10 protein levels between ALL and CLL underscores a potentially divergent role for this protease in the pathogenesis or progression of these two distinct hematological malignancies." (PMID 40746920, 2025).
retinopathy (1 paper, 2022). "First, we checked the ADAM10 activity in retinae collected from mice subjected to oxygen-induced retinopathy (OIR)." (PMID 36185601, 2022).
ADAM10 also shares sentences with these, for which no sentence is quoted: autism spectrum disorder (4 papers); schizophrenia (4); T-cell acute lymphoblastic leukemia (4); hypopharyngeal carcinoma (3); squamous cell carcinoma (3); Cirrhosis (2); fibrosarcoma (2); nasopharyngeal carcinoma (2); non-Hodgkin lymphoma (2); Onset (2); adenocarcinoma (1); alopecia (1); amyotrophic lateral sclerosis (1); astrocytic tumor (1); autism (1); bladder urothelial carcinoma (1); brain cancer (1); breast (1); cavernous cerebral malformations (1); cerebral amyloid angiopathy (1); cerebral infarction (1); cheilitis (1); childhood tumor (1); chronic leukemia (1); Classical Hodgkin Lymphoma (1); CNS tumour (1); cognitive disorder (1); coronary atherosclerosis (1); demyelination (1); diffuse intrinsic pontine glioma (1).
A further 44 diseases each share a sentence with ADAM10 in 1 paper.